NAMPT (nicotinamide phosphoribosyltransferase)
Diseases named in the same sentence as NAMPT in open-access papers (continued):
Sharing a sentence is not in itself a finding about the gene and the disease.
cancer (continued). "Emerging experimental results have also indicated the involvement of NAMPT in regulating chemoresistance in cancer." (PMID 35565188, 2022). "In this review article, we provide an overview of the up-to-date knowledge regarding NAMPT-mediated biological effects across cancers." (PMID 35565188, 2022). "The salvage pathway constitutes the main source of NAD+ in cancer cells, and the nicotinamide phosphoribosyltransferase (NAMPT) is the bottleneck enzyme and the main regulator of intracellular NAD+." (PMID 35681770, 2022). "NAMPT can facilitate tumor initiation and progression and it can induce cancer stem cell-like properties in colon cancer and glioma." (PMID 35515130, 2022). "Overexpression of NAMPT accompanied by increased levels of NAD+ promotes cancer cell survival by making cells resistant to anti-cancer reagents." (PMID 33609766, 2021). "NAMPT plays an essential role in NAD(+) biosynthesis in cancer cells and can regulate cellular metabolism, such as altered carbohydrate metabolism in cancer cells." (PMID 34229638, 2021). "Because of the complex network of pathways in which NAD+ is essential, the important role of NAD+ and its key generating enzyme, NAMPT, in cancer is understandable." (PMID 33384409, 2021). "SIRT1 with NAMPT is overexpressed in many cancers such as colorectal cancer, prostate cancer, and gliomas." (PMID 33609766, 2021). "One of the cancer therapeutic strategies targeting NAD metabolism is the use of nicotinamide phosphoribosyltransferase (NAMPT) inhibitors." (PMID 34946971, 2021). "In the context of cancer, an immunosuppressive microenvironment is generated when NAMPT inhibitors are given in combination with immunotherapy." (PMID 33384409, 2021). "Several mechanisms were reported to trigger cancer cell death in response to NAD depletion by NAMPT inhibitors." (PMID 34068917, 2021). "Nicotinamide phosphoribosyltransferase (NAMPT) is up-regulated in different types of cancers such as CRC, resulting in an increase in the NAD(H) pool size and the NAD+/NADH ratio." (PMID 34680038, 2021). "NAMPT is overexpressed in the cancer stem cells, the higher the level of this transferase, the worse is the prognosis in terms of cancer development." (PMID 33804163, 2021). "In this section, we report the downstream effects of NAD deprivation in cancer cells and combination strategies that were shown to potentiate the NAMPT inhibitors, eliciting a more pronounced antitumor response." (PMID 34068917, 2021). "NAMPT promotes the proliferation and survival of rapidly dividing cancer cells by elevating NAD levels and enhancing glycolysis." (PMID 33912035, 2021). "Research also shows that NAMPT plays a very important role in regulating the functioning of cancer stem cells, and PARPs and SIRTs also participate in the whole process." (PMID 33804163, 2021). "For this reason, cancer metabolism rewiring is often accompanied by the upregulation of NAMPT, the key-limiting enzyme that catalyzes the first reversible step in NAD biosynthesis from nicotinamide (Nam)." (PMID 34073463, 2021). "NAMPT is the major NAD+ biosynthetic enzyme and has been implicated in cancer stemness, as well as redox homeostasis and DNA repair." (PMID 33889302, 2021). "Given its pleiotropic role in cancer pathogenesis, NAMPT has long been considered an attractive therapeutic target for cancer treatment." (PMID 34068917, 2021). "USP22 can exert its cancer-promoting effect by upregulating the nicotinamide phosphoribosyltransferase (NAMPT)/SIRT1, AKT and ERK signaling pathways involved with c-Myc activation." (PMID 34179009, 2021). "Specifically, we found that SIRT6 enhances NAMPT enzymatic activity through direct protein deacetylation, protecting cancer cells against oxidative stress." (PMID 34068917, 2021).
cancer (continued). "Except IDO and TDO various enzymes of the kynurenine pathway have been identified as potential targets in cancer treatment such as nicotinamide phosphoribosyltransferase (NMPRT), nicotinamide N-methyltransferase (NNMT) and poly-(ADP-ribose) polymerase (PARP)." (PMID 34356899, 2021). "On the other side, cancers displaying genetic alterations that suppress NAPRT activity are exquisitely vulnerable to NAMPT inhibitors’ monotherapy." (PMID 34068917, 2021). "NAMPT overexpression has been described in cancer cells and pharmacological NAMPT targeting has shown anti-tumor effects in AML and WM." (PMID 33669329, 2021). "Later on, cancer cell line profiling and genomic profiling of compound-resistant clones identified NAMPT as the target enzyme of STF-31." (PMID 34068917, 2021). "For instance, NAMPT is essential for survival of tumor cells, and is considered a rational target in cancer." (PMID 34662475, 2021). "NAMPT inhibition facilitates cancer cell killing likely because cancer cells have a higher demand for NAD+." (PMID 34095234, 2021). "The rationale was mainly supported by the over-expression of NAMPT in cancer cells, as extensively described by us and by several research groups." (PMID 34421911, 2021). "Currently, inhibition of NAMPT as a therapeutic strategy in cancer has attracted more and more attention." (PMID 34238288, 2021). "The salvage pathway is important for the maintenance of NAD+ level in cancer cells and involves 2 major enzymes, one of which is phosphoribosyltransferase (NAMPT) and the other is nicotinate phosphoribosyltransferase (NAPRT)." (PMID 33392072, 2020). "Inhibitors of NAMPT are currently used in the clinic for the treatment of cancers, in combination with genotoxic drugs." (PMID 32722390, 2020). "Nonetheless, the metabolic plasticity of cancer cells generally leads to acquired resistance to NAMPT inhibition, and increased expression or activity of QPRT is a novel resistance mechanism." (PMID 33613454, 2020). "Since inhibitor molecules are available for NAMPT, our knowledge on the targetability of NAD+ synthesis for cancer therapy comes from experiments with the NAMPT inhibitor compounds, FK866 and GMX1777." (PMID 32392755, 2020). "Overexpression of NAMPT is observed in several types of malignant tumors, which supplies back-up NAD+ to sustain cellular proliferation and promote resistance to therapeutic agents." (PMID 32295316, 2020). "Mechanistically, NAMPT inhibitors induce cell death in cancer cells by depleting intracellular NAD+ and ATP levels and inhibiting glycolysis and glucose uptake." (PMID 32295316, 2020). "Increased NAD+ and aberrant NAMPT overexpression promotes glycolysis, which fuels the growth and survival of cancer cells." (PMID 32295316, 2020). "Though NAMPT inhibitors as a monotherapy are promising candidates for cancer therapy, drug resistance and toxicity to normal tissues when used at high concentration remain a major hurdle." (PMID 32295316, 2020). "Recently, some studies have indicated that NAMPT acts as a regulator of cancer invasion and metastasis, which is one of the hallmarks of malignant cancer cells." (PMID 32005247, 2020). "Upregulated NAMPT boosts the initiation and progression of various cancers, and the interference of NAMPT by chemical inhibitors or by genetic modification decreases the survival of cancer cells." (PMID 32005247, 2020). "Consistently, the dataset (Hong Colorectal) from Oncomine Cancer Microarray Database indicated that the expression levels of NAMPT were significantly reduced in advanced stage (M1 stage) of CRC patients compared with early stage (M0 stage)." (PMID 32005247, 2020).
cancer (continued). "Several information about NAPRT expression and regulation emerged in tumors, in relation to the efficacy of NAMPT inhibitors (NAMPTi) as potential anti-cancer agents, as described in the dedicated section NAMPT and NAPRT in Tumors." (PMID 32266141, 2020). "Further evidence for the importance of the NAMPT-mediated NAD+ synthesis pathway in the retina comes from the cancer field." (PMID 32454935, 2020). "Inhibition of nicotinamide phosphoribosyltransferase (NAMPT) is an attractive therapeutic strategy for targeting cancer metabolism." (PMID 32785052, 2020). "As an antioxidant, cinnamaldehyde can inhibit the spread of cancer by inhibiting the expression of extracellular and intracellular fat factor nicotinamide phosphoribosyltransferase." (PMID 33536908, 2020). "In certain cancers, NAMPT expression has been shown to promote carcinogenesis and is associated with worse prognosis." (PMID 32908120, 2020). "Untransformed cells are less sensitive to ROS induction upon NAMPT inhibition, suggesting a therapeutic window that can be used to target a specific vulnerability in cancer cells." (PMID 32722390, 2020). "As preclinical studies with NAMPT showed encouraging results, the clinical efficacy and safety of NAMPT inhibitors has been tested in cancer patients." (PMID 32111066, 2020). "Aberrant expression of PAK4 and NAMPT is driven by a variety of genetic changes play a critical role in the survival of several cancers." (PMID 31795447, 2019). "This in principle can provide a therapeutic window for cancer cell selective inhibition of NAMPT and resultant metabolic collapse of tumor cells." (PMID 31795447, 2019). "Exposure of cancer cells to NAMPT inhibitors strongly decreases NAD cell content, followed by ATP decline that ultimately leads to cell death." (PMID 31803365, 2019). "To analyze the nucleotide sequence of the NAMPT gene by Sanger sequencing, we performed reverse-transcription into the cDNA library using mRNA extracted from the resistant cancer cell lines and their parent cell lines." (PMID 31123329, 2019). "NAMPT has been shown to be over-expressed in various cancer types including melanoma and cancers of the breast, colon, esophagus, stomach, pancreas, ovary, prostate, and thyroid." (PMID 30856230, 2019). "In fact, many types of cancer cells have been shown to highly express NAMPT, reflecting potentially increased dependence on this pathway due to high NAD+ utilization and in some cases, loss of expression of other key NAD+ biosynthetic enzymes." (PMID 32010616, 2019). "Frequency of NAMPT expression correlated with pathological stage, consistent with published literature regarding its role in cancer progression." (PMID 30856230, 2019). "In cancer cells, NAMPT inhibitors affect glycolysis, oxidative phosphorylation, serine biosynthesis and one-carbon metabolism, the pentose phosphate pathway, amino acid metabolism, purine and pyrimidine metabolism, and fatty acid and lipid synthesis." (PMID 32010616, 2019). "Here we aimed to investigate the effect of miR-381, which was predicted by bioinformatics tools to target NAMPT, in controlling the growth of cancer cells." (PMID 31611752, 2019). "Correlation between NAPRT/NAMPT expression and clinicopathological features in cancer tissues from 261 CRC patients." (PMID 31448236, 2019). "In murine cancer models, macrophage colony stimulating factor was shown to increase NAMPT expression in myeloid cells which, in turn, negatively regulated CXCR4 expression in hematopoietic cells in the bone marrow." (PMID 32010616, 2019). "Crosstalk between NAMPT and oncogenic signaling pathways has been reported in several cancer models." (PMID 32010616, 2019). "Given the critical role that NAD+ plays in the growth and survival of malignant cells, NAMPT is an attractive therapeutic target in cancer." (PMID 32010616, 2019).
cancer (continued). "NAMPT over-expression has been shown in various cancers and its inhibition decreases cancer cell growth, making it an attractive therapeutic target." (PMID 30856230, 2019). "We found the highest NAMPT expression in the thyroids of patients with GO (n = 20) and cancers (n = 40)." (PMID 29546048, 2018). "FK866 has been used broadly in the cancer field and others to study the impact of NAMPT inhibition on various processes including cellular viability and immune signaling, inflammation, and energy metabolism." (PMID 29905535, 2018). "In post hoc analysis, we found the highest NAMPT expression in the thyroids of patients with GO and cancers." (PMID 29546048, 2018). "NAMPT has become an attractive target for cancer treatment due to its role in controlling sirtuins’ activity in tumors, and its inhibitor, APO866 has been used in Phase II clinical trials." (PMID 30283496, 2018). "The precise molecular mechanisms by which cancer cells become cross-resistant to NAMPT inhibitors remain to be elucidated." (PMID 29662658, 2018). "Due to its role in maintaining NAD+ levels in tumors, NAMPT has become an attractive target for cancer treatment and inhibition of NAMPT impairs pancreatic tumor growth." (PMID 30283496, 2018). "The build-up of metabolites before the enzyme, coupled with the decrease in metabolites observed downstream in response to NAMPT inhibition corroborates previous studies in cancer cells and C2C12s12,19." (PMID 30607371, 2018). "Increased expression of NAMPT has been observed in many cancer types and previous studies have shown that inhibition of NAMPT leads to the attenuation of tumour growth and induction of apoptosis due to NAD+ depletion." (PMID 28086232, 2017). "NAMPT inhibition also leads to attenuation of glycolysis, resulting in further perturbation of carbohydrate metabolism in cancer cells." (PMID 29245920, 2017). "NAMPT represents a promising therapeutic target for the development of potential novel cancer drugs." (PMID 28420117, 2017). "Nicotinamide phosphoribosyl-transferases (NAMPT) are enzymes that play a role in targeting cancer metabolism, while beta lactamases are involved in bacterial resistance to beta-lactam antibiotics." (PMID 28634829, 2017). "This is why NAD+ dependence renders cancer cells more sensitive to NAMPT inhibition than normal cells." (PMID 27462772, 2016). "Nicotinamide phosphoribosyltransferase (NAMPT) is a rate-limiting enzyme in the biosynthesis of nicotinamide adenine dinucleotide and has a crucial role in cancer cell metabolism." (PMID 28097126, 2016). "Overexpression of visfatin/NAMPT in epithelial cells has been shown to induce epithelial to mesenchymal transition, a morphological and functional switch that confers cancer cells an increased metastatic potential." (PMID 27293305, 2016). "Lowering intratumor NAD+ concentration is currently considered a promising strategy to treat cancer and major efforts are directed to the identification of clinically applicable NAMPT inhibitors." (PMID 26658104, 2016). "Secondly, NAMPT allows NAD+ synthesis by a salvage pathway in a dose dependent manner, and NAMPT is known to be increased in several cancers." (PMID 27462772, 2016). "Among them, NAMPT has been extensively characterized and is a prospective therapeutic target in human cancer." (PMID 26675378, 2016). "Several NAMPT inhibitors have been synthesized already, and some of them were tested in advanced clinical trials as possible cancer therapeutics." (PMID 26767650, 2016). "The prototypical NAMPT inhibitor FK866 effectively lowers NAD+ levels in cancer cells, reducing the activity of NAD+-dependent enzymes, lowering intracellular ATP, and promoting cell death." (PMID 26542945, 2015). "Understanding the relationship of NAMPT and survivin with the cancer cell cycle provides the potential therapeutic targets for novel inhibitors." (PMID 25946974, 2015).
cancer (continued). "Taken together, NAMPT exemplifies a promising therapeutic target for the development of potential novel cancer drugs." (PMID 25486521, 2014). "Significantly decreased levels of butyrylcarnitine in a dose-dependent fashion suggest a NAMPT inhibition effect on de novo fatty acid synthesis, which was earlier reported to be reduced in different cancer cells when treated with FK866." (PMID 25486521, 2014). "In the current study, we used a global mass spectrometry–based metabolomic approach to investigate the effects of FK866, a small molecule inhibitor of NAMPT currently in clinical trials, on metabolic perturbations in human cancer cells." (PMID 25486521, 2014). "These differentially-expressed genes were denoted as NAMPT-influenced genes with gene ontology analysis indicating enriched cancer-related pathways." (PMID 25146220, 2014). "In this study, we have shown that NAMPT inhibition leads to numerous metabolic perturbations in cancer cells and demonstrated resourcefulness of global metabolomics as a useful data extraction protocol for studying cellular metabolism." (PMID 25486521, 2014). "The results of this study support knowledge about an important role of NAMPT in cancer cells' proliferation and its attractiveness as anticancer target for new, more specific, and less toxic drug molecules." (PMID 25486521, 2014). "As a result, the down-regulation of NAMPT sensitizes cancer cells to DNA-damaging agents and apoptosis." (PMID 25486521, 2014). "GNE-618 is a novel small molecule that potently inhibits NAMPT activity and exhibits efficacy in xenograft models of cancer." (PMID 25285661, 2014). "The NAD+ biosynthetic enzyme NAMPT has been implicated in linking NAD+ metabolism and the inflammatory cytokine response of monocytes and macrophages and to play a regulatory role in cancer cell motility." (PMID 24824795, 2014). "Recent studies have demonstrated that NAMPT-mediated NAD biosynthesis in cancer cells plays a crucial role in several physiological processes, including metabolism, energy generation, survival, apoptosis, DNA repair, and inflammation." (PMID 25486521, 2014). "We interrogated known microarray data sets to define NAMPT knockdown-influenced gene expression to demonstrate that reduced NAMPT expression strongly dysregulates cancer biology signaling pathways." (PMID 25146220, 2014). "Some cancer cells maintain intracellular NAD levels by overexpressing NAMPT which has been shown in different cancer types, such as colorectal and breast cancer." (PMID 24603648, 2014). "In the current study, we wanted to further assess the global effects of NAMPT inhibition by FK866 on cancer metabolism by using global mass spectrometry–based metabolic profiling." (PMID 25486521, 2014). "First, we identified differentially expressed genes utilizing microarray data from two independent human cell lines (primary and cancer cells) and wild-type (WT) cells and NAMPT knock down (KD) cells." (PMID 25146220, 2014). "Thirty-nine NAMPT-influenced genes were identified as being commonly differentially expressed in tumor tissues and comprised a multi-molecular cancer outcome predictor." (PMID 25146220, 2014). "NAMPT inhibitors are being used in clinical trials as anti-cancer agents and nicotinamidases are attractive targets to the development of drugs for infectious diseases and anti-parasitic therapies." (PMID 23724078, 2013). "In humans, NAMPT is widely studied due to its involvement in inflammation and disease such as cancer." (PMID 23724078, 2013). "Emerging data implicate nicotinamide phosphoribosyl transferase (NAMPT) in the pathogenesis of cancer and inflammation." (PMID 22490786, 2012). "Interestingly, NAMPT suppression ameliorates the adverse effects induced by cancer stem-like cells and hinders OC cell development treated with cisplatin chemotherapy in vitro and in vivo." (PMID 40076482, 2025).